DHCR7-DT (DHCR7 divergent transcript)
Synonyms: AP; lnc; AP002387.2; RP11-660L16.2
Gene: Long non-coding RNA gene on chromosome 11 (71,448,542 to 71,452,165, forward strand). Ensembl gene ENSG00000254682.
Diseases named in the same sentence as DHCR7-DT in open-access papers:
DHCR7-DT is named in the same sentence as 16 diseases in open-access papers, as found by Europe PMC text mining. Sharing a sentence is not in itself a finding about the gene and the disease.
DHCR7-DT shares sentences with these, for which no sentence is quoted: pertussis (20 papers); infection (17); tumor (3); alveolitis (1); atypical hemolytic-uremic syndrome (1); cancer (1); coronary artery disease (1); diphtheria (1); hyperlipidemia (1); Hypertension (1); monoclonal gammopathy (1); myocardial infarction (1); neurodevelopmental disorder (1); papillary thyroid carcinoma (1); paroxysmal nocturnal hemoglobinuria (1); tetanus (1).